C17orf100 (chromosome 17 open reading frame 100)
Synonyms: LOC388327
Tractability: No criterion of Open Targets' tractability assessment is met for any kind of drug.
Gene: Protein-coding gene on chromosome 17 (6,651,762 to 6,693,202, forward strand). Ensembl gene ENSG00000256806.
Subcellular location (Human Protein Atlas): Nucleoplasm; Cytokinetic bridge; Cytosol
Genetic constraint (gnomAD): Loss-of-function variants: 2 observed, 1.6 expected, observed/expected ratio (o/e) 1.25, 90% interval 0.42 to 1.91. That is too few expected variants to judge how well the gene tolerates losing a copy. Missense variants: 168 observed, 147.1 expected, observed/expected ratio (o/e) 1.14, 90% interval 1.01 to 1.3. Synonymous variants: 87 observed, 75.21 expected, observed/expected ratio (o/e) 1.16, 90% interval 0.97 to 1.38.
Homologues: Orthologues: mouse 4930563E22Rik (68% identical), rat 4930563E22Rik (67% identical).